CNNM1 (cyclin and CBS domain divalent metal cation transport mediator 1)
Description:
Probable metal transporter.
Synonyms: ACDP1; SLC70A1; CLP-1
Tractability: Antibody: UniProt places it where antibodies can reach, with medium confidence; UniProt predicts a signal peptide or a membrane-spanning region; its Gene Ontology location is reachable by antibodies, with medium confidence; the Human Protein Atlas places it where antibodies can reach. PROTAC: ubiquitination databases record sites on it.
Gene: Protein-coding gene on chromosome 10 (99,329,356 to 99,394,330, forward strand). Ensembl gene ENSG00000119946.
Subcellular location: Cell membrane
Subcellular location (Human Protein Atlas): Cytosol; Plasma membrane
Gene Ontology:
Molecular function: protein binding; transmembrane transporter activity
Biological process: magnesium ion homeostasis; transmembrane transport
Cellular component: plasma membrane; dendrite; neuronal cell body
Genetic constraint (gnomAD): Loss-of-function variants: 25 observed, 56.55 expected, observed/expected ratio (o/e) 0.44, 90% interval 0.32 to 0.62. The upper end of that interval is the gene's LOEUF score, 0.62, which puts it in group 2 of 6, group 1 being the genes least tolerant of losing a copy. Missense variants: 649 observed, 841.11 expected, observed/expected ratio (o/e) 0.77, 90% interval 0.72 to 0.82. Synonymous variants: 316 observed, 339.59 expected, observed/expected ratio (o/e) 0.93, 90% interval 0.85 to 1.02.
Homologues: Orthologues: chimpanzee CNNM1 (99% identical), macaque CNNM1 (98% identical), dog CNNM1 (96% identical), pig CNNM1 (95% identical), rabbit CNNM1 (95% identical), mouse Cnnm1 (95% identical), rat Cnnm1 (94% identical), guinea pig CNNM1 (76% identical), tropical clawed frog cnnm1 (67% identical), zebrafish cnnm1 (51% identical), Drosophila melanogaster uex (30% identical), Caenorhabditis elegans cnnm-3 (23% identical), and 2 more. Paralogues in human: CNNM2 (44% identical), CNNM4 (38% identical), CNNM3 (35% identical).
Diseases named in the same sentence as CNNM1 in open-access papers:
CNNM1 is named in the same sentence as 8 diseases in open-access papers, as found by Europe PMC text mining. Sharing a sentence is not in itself a finding about the gene and the disease. The quoted sentences say what the papers report.
Infertility (2 papers, 2016 to 2023). "In this study, we showed that cnnm-1; cnnm-3 mutant worms displayed pleiotropic phenotypes, such as infertility due to a gonadogenesis defect, shortened lifespan, and small body size." (PMID 27564576, 2016).
hepatocellular carcinoma (1 paper, 2022). A malignant tumor that arises from hepatocytes. "For CNNM1, it was reported that CNNM1 could be regulated by SNHG7 and miR-9-5p to promote the progression of hepatocellular carcinoma." (PMID 36406127, 2022).
male infertility (1 paper, 2023). The inability of the male to effect fertilization of an ovum after a specified period of unprotected intercourse. "We demonstrate our analyses’ potential to identify novel highly germ cell–specific markers (TSPY4 and LUZP4 for spermatogonia; HMGB4 for round spermatids) and identified putatively misregulated genes in male infertility (RWDD2A, CCDC183, CNNM1, SERF1B)." (PMID 36446526, 2023).
cancer (4 papers, 2015 to 2025). A tumor composed of atypical neoplastic, often pleomorphic cells that invade other tissues. "The mutation rates of different MHGs varied widely across cancer tissues, with ANK3 having the highest mutation rate (47%), followed by KEL (18%), TRPM7 (16%), KCNA1 (13%), CNNM2 (9%), CNNM1 (9%), TFAP2B (9%), CNNM4 (9%), XK (7%), and EDN3 (5%)." (PMID 41174507, 2025). "Similar cytoplasmic functions were found for CHROMR in certain cancers where it targets miR-27b-3p, miR-186-5p, and miR-1299, repressing cell cycle-regulator genes CNNM1, MET, and NCAPG2, leading to accelerated cancer growth and progression." (PMID 40559622, 2025). "In previous reports, CNNM2, one member of the CNNM family, which contains four integral membrane proteins (CNNM1‐4), played a unique role in maintaining intracellular Mg2+ homeostasis and for its biological functions related to various cancers." (PMID 36408691, 2023). "EDN3, TFAB2B showed high levels of methylation in almost all cancers, while CNNM1, CNNM2 and KCNA1 showed high levels of methylation in at least half (7 or more) of the cancers." (PMID 41174507, 2025). "In cancer, CHROMR binds additional miRNAs (e.g., miR-27b-3p, miR-186-5p, miR-1299) that repress cell cycle regulators such as CNNM1, MET, and NCAPG2, thereby promoting tumor proliferation and metastasis." (PMID 40559622, 2025).
tumor (4 papers, 2022 to 2025). "How TOB1-AS1 promotes cell invasion and tumor metastasis and whether CNNM1 plays a role require further study." (PMID 39051548, 2024). "Using TCGA PanCancer Atlas data accessed via cBioPortal, we assessed mRNA expression (z-score ≥2) in tumor samples relative to normal tissue for all PRLs (PTP4A1–3) and CNNMs (CNNM1–4)." (PMID 40463094, 2025).
CNNM1 also shares sentences with these, for which no sentence is quoted: Alzheimer disease (1 paper); colon cancer (1); Jalili syndrome (1).